PSPH (phosphoserine phosphatase)
Description:
Catalyzes the last irreversible step in the biosynthesis of L-serine from carbohydrates, the dephosphorylation of O-phospho-L-serine to L-serine. L-serine can then be used in protein synthesis, to produce other amino acids, in nucleotide metabolism or in glutathione synthesis, or can be racemized to D-serine, a neuromodulator. May also act on O-phospho-D-serine (Probable).
Synonyms: PSP; PSPHD
Tractability: Small molecule: a structure with a bound ligand is known; it has a high-quality binding pocket. PROTAC: ubiquitination databases record sites on it; its protein half-life has been measured.
Target class: Enzyme; Hydrolase
Gene: Protein-coding gene on chromosome 7 (56,010,312 to 56,051,604, reverse strand). Ensembl gene ENSG00000146733.
Subcellular location: Cytoplasm, cytosol
Subcellular location (Human Protein Atlas): Cytosol
Pathways (Reactome):
Metabolism: Serine metabolism
Gene Ontology:
Molecular function: identical protein binding; L-phosphoserine phosphatase activity; magnesium ion binding; protein homodimerization activity
Biological process: L-serine biosynthetic process; L-serine metabolic process; response to mechanical stimulus; response to nutrient levels; response to testosterone
Cellular component: cytosol
Genetic constraint (gnomAD): Loss-of-function variants: 16 observed, 22.86 expected, observed/expected ratio (o/e) 0.7, 90% interval 0.47 to 1.06. The synonymous counts are far from expectation, so gnomAD's model fits this gene poorly and the ratio says little. Missense variants: 216 observed, 268.2 expected, observed/expected ratio (o/e) 0.81, 90% interval 0.72 to 0.9. Synonymous variants: 67 observed, 95 expected, observed/expected ratio (o/e) 0.71, 90% interval 0.58 to 0.86.
Gene-disease validity (ClinGen):
ClinGen rates the evidence that PSPH causes each of these diseases.
neurometabolic disorder due to serine deficiency (autosomal recessive): Moderate. Serine-deficiency syndrome is a very rare infantile-onset potentially treatable neurometabolic disorder characterized clinically by microcephaly, neurodevelopmental disorders and seizures.
Homologues: Orthologues: chimpanzee PSPH (99% identical), macaque PSPH (98% identical), pig PSPH (96% identical), dog PSPH (95% identical), rabbit PSPH (95% identical), rat Psph (95% identical), mouse Psph (94% identical), guinea pig PSPH (91% identical), tropical clawed frog psph (80% identical), zebrafish psph (70% identical), Caenorhabditis elegans Y62E10A.13 (51% identical), Drosophila melanogaster aay (48% identical).
Diseases named in the same sentence as PSPH in open-access papers:
PSPH is named in the same sentence as 60 diseases in open-access papers, as found by Europe PMC text mining. Sharing a sentence is not in itself a finding about the gene and the disease. The quoted sentences say what the papers report.
breast carcinoma (19 papers, 2012 to 2025). "Compared to breast cancer cells with low bone metastatic activity, the expression of serine metabolic enzymes (including PHGDH, PSAT1 and PSPH) was increased in breast cancer cells with high bone metastatic activity." (PMID 36998464, 2023). "Tumor PSPH positivity, stromal PSPH positivity, and stromal SHMT-1 negativity are linked to decreased survival in TNBC and HER-2 breast cancers." (PMID 35565690, 2022). "Hypoxia has been shown to induce expression of PHGDH, PSAT1 and PSPH in breast cancer cells and PHGDH has been shown to be overexpressed in various cancer types, including colorectal, non-small cell lung, cervical and breast cancers." (PMID 36226069, 2022). "Compared with breast cancer cells with weak bone metastasis activity, the expression of de novo serine synthesis enzymes, including PHGDH, PSAT1, and PSPH, is increased in breast cancer cells with high bone metastasis activity." (PMID 33926551, 2021). "The level of PSPH has the relationship with breast cancer and lacrimal gland adenoid cystic carcinoma." (PMID 31057610, 2019). "Core metabolic prognostic signatures are identified, comprising NUDT1 and GAPDH in kidney renal cell carcinoma and SQLE, ALG3 and PSPH in two independent breast carcinoma cohorts." (PMID 27358048, 2016). "We used western blotting and immunohistochemistry to examine five serine-/glycine-metabolism–associated proteins (PHGDH, PSAT, PSPH, SHMT, and GLDC) in six breast cancer cell lines and 709 breast cancer cases using tissue microarray (TMA)." (PMID 24979213, 2014). "Specifically, we sought to estimate differences in the expression of two suspected good prognosis genes (ACOX2 and MUC1) and six suspected poor prognosis genes (FAM177A1, GSTT2, PSPH, PSPHL, SQLE, and TYMS) by race, and to examine their associations with risk of breast cancer recurrence." (PMID 29228969, 2017). "Appreciably, breast cancer stromal components expressed elevated PSPH, SHMT1, and GLDC levels." (PMID 24979213, 2014). "Thus, we hypothesize that a breast cancer subset with high expression of enzymes associated with serine metabolism (PHGDH and PSPH) could present with an aggressive behavior." (PMID 24979213, 2014). "In terms of mechanism, the decreased expression of kinase C zeta (PKC-ζ) in bone-derived breast cancer cells led to the upregulation of PHGDH, PSAT1 and PSPH, consequently promoted the utilization of glutamine through serine biosynthesis." (PMID 36998464, 2023). "One breast cancer study found that PHGDH and PSPH are highly expressed in in vitro TNBC, and these, along with SHMT-1, are also elevated in stromal TNBC tumors." (PMID 35565690, 2022). "Among 5 different cancer cell lines, MCF7 (CD44-low breast cancer) and MDA-MB-231 (CD44-high breast cancer) expressed either PHGDH or PSAT1, and PSPH." (PMID 29674746, 2018). "Cancer cells with LKB1 loss increase the expression of phosphoserine aminotransferase 1 (PSAT1), phosphoserine phosphatase (PSPH) and serine hydroxylmethyltransferase (SHMT1/2) involving de novo serine synthesis pathway (SSP) in breast cancer." (PMID 28931725, 2017). "Former studies have illustrated that serine biosynthesis has a key role in bone metastatic breast cancer, and three enzymes, PSAT1, phosphoserine phosphatase and phosphoglycerol dehydrogenase, are in charge of the phosphorylation pathway of L-serine biosynthesis." (PMID 36105075, 2022). "Regarding bone metastasis, breast cancer cells show increased serine biosynthesis through the expression of phosphoglycerate dehydrogenase (PHGDH), phosphoserine aminotransferase, (PSAT1), and phosphoserine phosphatase (PSPH)." (PMID 33915900, 2021). "TMA showed that the TNBC-type breast cancer tissues highly expressed PHGDH, PSPH, and SHMT1, but not the luminal-A-type tissues (p<0.001)." (PMID 24979213, 2014).
breast carcinoma (continued). "Using data from the Cancer Cell Line Encyclopedia (CCLE) and our own qPCR and western blots, we found that breast cancer cell lines robustly maintain the low-PSAT1 phenotype of luminal tumors, while the differences in PHGDH and PSPH were less pronounced or absent." (PMID 35045283, 2022).
hepatocellular carcinoma (9 papers, 2019 to 2023). A malignant tumor that arises from hepatocytes. "High tumor cell-specific PSPH expression was observed in hepatocellular carcinoma and associated with inferior patient survival." (PMID 31186416, 2019). "PSPH is a c-Myc-mediated enzyme and increases as hepatocellular carcinoma progression to a malignant clinical stage." (PMID 31861486, 2019). "Constitutive PSPH expression has been shown to induce tumor progression in an in vivo model of hepatocellular carcinoma, while shRNA targeting of PSPH reduced the tumor burden in the same model." (PMID 31186416, 2019). "Some researchers have reported that abnormal expression of PSPH is strongly relevant to the hepatocellular carcinoma patients' mortality as well as the critical importance on cMyc-induced cancer progression both in vitro and in vivo." (PMID 31057610, 2019). "Notably, a high expression of PSPH correlates with disease progression and mortality in patients with hepatocellular carcinoma, indicating that the PSPH protein is a potential prognostic biomarker for this cancer." (PMID 34445444, 2021). "Overexpression of PSPH was found in hepatocellular cancer and colorectal cancer." (PMID 31861486, 2019). "Additionally, several studies reported that augmented PSPH level is correlated with the prognosis in multiple cancers including cutaneous squamous cell carcinoma, breast cancer, non-small cell lung cancer, colorectal cancer and hepatocellular carcinoma." (PMID 34979926, 2022). "In human hepatocellular carcinoma (HCC), cMYC-induced PSPH upregulation is a determining factor for the oncogenic activity of cMYC, and an important predictor of HCC patients’ survival." (PMID 33801846, 2021). "C-MYC directly controls the transcription of PHGDH, PSAT1, PSPH, SHMT1, and SHMT2 in human hepatoma and HeLa cells." (PMID 37949226, 2023).
lung cancer (8 papers, 2019 to 2026). A malignant neoplasm involving the lung. "Phosphoserine phosphatase (PSPH) is a key factor in the malignant progression of lung cancer cells and cancer drug resistance." (PMID 39735553, 2024). "Elevation of key SSP enzymes, such as PHGDH, PSAT1, and PSPH, is an important factor in the malignant progression of lung cancer cells and cancer drug resistance." (PMID 36699468, 2022). "The increased expression of phosphoglycerate dehydrogenase (PHGDH) and the upregulation of both phosphoserine aminotransferase 1 (PSAT1) and phosphoserine phosphatase (PSPH) highlight the importance of the serine biosynthesis pathway in lung cancer biology." (PMID 31803611, 2019). "This is an important mechanism by which PSPH promotes lung cancer progression in vitro and in vivo." (PMID 36699468, 2022). "Phosphoserine phosphatase (PSPH), whose role in lung cancer has already been explored, shows a relatively high percentage of alteration in the prostate cancer cohort, up to 11% of the specimens, mostly due to gene overexpression (except for a few cases in which the gene is deleted)." (PMID 35201488, 2021). "However, the role of PSPH in non‐small cell lung cancer (NSCLC) is unclear." (PMID 30977310, 2019). "In this study, we identify key enzymes in the serine synthesis pathway (SSP), namely PHGDH, PSAT1 and PSPH, as well as the serine transporter SLC1A4, which are significantly overexpressed in lung cancer and correlate with poor patient prognosis." (PMID 41702885, 2026). "There is also a study showing the increased protein level of all three proteins (fold change: PHGDH: +3.62; PSAT 1: +6.94: PSPH: +1.27) in lung cancer tissue, when compared to corresponding non-tumorous tissue." (PMID 37376060, 2023).
glioblastoma (5 papers, 2014 to 2025). The most malignant astrocytic tumor (WHO grade IV). "In the SSP, SHMT2 and PSPH are upregulated but the upstream enzyme PSAT1 is downregulated in glioblastoma." (PMID 36175487, 2022). "SHMT2 and PSPH were upregulated and the upstream enzyme PSAT1 was downregulated, suggesting that SHMT2 and PSPH play key roles in activation of the SSP in glioblastoma." (PMID 36175487, 2022). "However, little is known about the role of PSPH in patients with glioblastoma." (PMID 36175487, 2022). "Collectively, alterations have been found in ~35% of lung cancers, in ~37% of melanomas, and 25% of glioblastoma (GBM) patients, in the latter with recurrent amplifications of PSPH gene in 12% of cases (TCGA copy number portal, p = 5.25 × 10−61)." (PMID 33801846, 2021). "Our results showed that SHMT2 and PSPH were upregulated in SSP, while their upstream enzymes PSAT1 or PHGDH were downregulated or unaffected in glioblastoma, suggesting that the SSP in glioblastoma might be independent of carbon flux from glycolysis." (PMID 36175487, 2022).
melanoma (5 papers, 2022 to 2025). A malignant, usually aggressive tumor composed of atypical, neoplastic melanocytes. "PSPH is associated with the development of various cancers and is a promising prognostic biomarker in different cancers such as advanced colorectal cancer, thyroid cancer and melanoma." (PMID 34979926, 2022). "Knocking down PSPH expression using short hairpin RNAs (shRNAs) markedly inhibited melanoma tumor growth and metastasis in both cell culture and mouse models." (PMID 39090094, 2024). "The serine biosynthesis pathway, which involves the enzymes phosphoglycerate dehydrogenase (PHGDH), phosphoserine aminotransferase 1 (PSAT1), and phosphoserine phosphatase (PSPH), is frequently upregulated in malignancies such as triple-negative breast cancer and melanoma." (PMID 40535116, 2025). "Key enzymes such as D-3-Phosphoglycerate dehydrogenase (PHGDH), phosphoserine aminotransferase 1 (PSAT1), and phosphoserine phosphatase (PSPH) are upregulated in melanoma, enhancing nucleotide synthesis, methylation reactions, and antioxidant defense via glutathione production." (PMID 40573249, 2025). "Similarly, in the PRJEB23709 melanoma anti-PD1 immunotherapy cohort, the levels of PSAT1, PSPH, and SHMT1/2 were significantly reduced in PR or CR patients treated with anti-PD1 compared with drug-resistant PD patients." (PMID 37223471, 2023).
breast tumors (4 papers, 2017 to 2023). "PHGDH was also among the top-scoring genes, and PSPH expression was also reduced in luminal breast tumors." (PMID 35045283, 2022). "Analysis of the proteome of human breast tumors also revealed very low levels of PHGDH and PSAT1 (but not PSPH) protein in luminal breast tumors." (PMID 35045283, 2022).
glioma (4 papers, 2010 to 2025). A benign or malignant brain and spinal cord tumor that arises from glial cells (astrocytes, oligodendrocytes, ependymal cells). "The results of immunohistochemical (IHC) staining showed that PHGDH, PSAT1, and PSPH expression levels in both low-grade gliomas and high-grade gliomas (GBM) are much higher than those in normal human brain tissue." (PMID 38098117, 2023). "Compared to the other clusters, gliomas in cluster 4 expresses significantly higher levels of PSPH and SHMT1 which were known culprits of aberrant serine and glycine production in malignant cancers." (PMID 36467068, 2022). "Further univariate analysis demonstrated that SHMT1, SARDH, and PSPH were hazardous prognostic factors for glioma." (PMID 36467068, 2022). "The staining figures revealed that the protein levels of SARDH and PSPH were higher in high-grade gliomas compared to low-grade gliomas, which was consistent with the results of the univariate analysis." (PMID 36467068, 2022). "In addition, analyses of The Gene Expression Omnibus (GEO) database (GSE4290; n = 180) showed that PSAT1 and PSPH genes are upregulated in human gliomas tissues, compared to normal tissues." (PMID 38098117, 2023). "Additionally, the strong immunohistochemistry signal of PSPH in high grade gliomas presented as an example that the dysregulated SMGMs could be used as pathological biomarkers to identify the most aggressive gliomas." (PMID 36467068, 2022). "The expression of 5 genes (VSTM2A, SEPT14, MRPS17, PSPH and CCT6A) was undetectable in all these gliomas, regardless of their amplification status." (PMID 21170331, 2010).
lung adenocarcinoma (4 papers, 2019 to 2023). A carcinoma that arises from the lung and is characterized by the presence of malignant glandular epithelial cells. "Additionally, we found increased protein expression of ATF4 and PHGDH, along with upregulated mRNA levels of PCK2, PHGDH, PSAT1, and PSPH, in DNM1L‐KO lung adenocarcinoma cell lines." (PMID 33152171, 2021).
colorectal cancer (3 papers, 2019 to 2022). A primary or metastatic malignant neoplasm that affects the colon or rectum. "Moreover, overexpression of PSPH is also a poor prognostic marker in colorectal cancer." (PMID 31861486, 2019).
liver cancer (3 papers, 2022 to 2025). An epithelial or non-epithelial malignant neoplasm that arises from the liver. "The results showed that knockdown of PSPH significantly inhibited the proliferative capacity of liver cancer cells in vitro." (PMID 39267787, 2024). "We also designed specific siRNA targeting PSPH and transfected it into liver cancer cells to further clarify its molecular functions in liver cancer." (PMID 39267787, 2024). "TRIM71 forms a protein complex with IGF2BP1, enhances mRNA stability of CEBPA with m6A-dependent manner, remodels PSPH and PSAT1 transcription, strengthens serine/glycine metabolism, and ultimately promotes liver cancer progression." (PMID 39267787, 2024). "TRIM71 activates the glycine/serine metabolism pathway by remodeling the transcription of PSPH and PSAT1, thereby controlling the oncofetal characteristics of liver cancer and tumor initiation and progression." (PMID 39267787, 2024). "TRIM71 binds to and stabilizes the mRNAs of CEBPA, remodels PSPH and PSAT1 transcription, enhances the serine/glycine metabolic pathway, and ultimately promotes liver cancer progression." (PMID 39267787, 2024). "Consistent with our recent findings in pediatric liver cancer, we also observed that CM272 markedly reduced the expression of amino acid metabolic enzymes (ASNS, PYCR1, BCAT2), as well as genes involved in the serine pathway (PHGDH, PSPH, PSAT1)." (PMID 39810240, 2025). "Importantly, ATRA or A-485 decreased mRNA levels of TRIM71, CEBPA, PSPH, PSAT1 and protein levels of TRIM71 and CEBPA, suggesting the transcriptional regulation of RXRA and EP300 to TRIM71 in liver cancer." (PMID 39267787, 2024). "Importantly, it forms a protein complex with IGF2BP1, which binds to and stabilizes CEBPA mRNA levels through an m6A-dependent manner, enhancing CEBPA mediated PSPH/PSAT1 transcription and remodeling serine/glycine metabolism, and ultimately accelerates liver cancer growth and tumorigenicity." (PMID 39267787, 2024). "Conversely, PSPH and PSAT1 mRNA levels and protein levels were dramatically upregulated in TRIM71 and YAP5SA + TRIM71 mice liver tumor tissues compared to the control group, and inhibition of TRIM71 or CEBPA decreased cellular serine and glycine levels in HuH-7 and Hep3B liver cancer cells." (PMID 39267787, 2024).
Williams syndrome (3 papers, 2011 to 2019). "Phosphoserine phosphatase (PSPH) mutations have been associated with phosphoserine phosphatase deficiency [MIM 614023], which results in pre- and postnatal growth retardation, moderate psychomotor retardation, and facial features suggestive of Williams syndrome." (PMID 24651765, 2014).
endometrial cancer (2 papers, 2012 to 2022). Primary or metastatic malignant neoplasm involving the endometrium (mucous membrane that lines the endometrial cavity). "Data from these assays performed on a panel of endometrial cancers from AA and CA confirmed the array findings for IGF1R, MUC20, and RRAD, but interestingly, qRT-PCR utilizing primers targeted to PSPH did not." (PMID 22783543, 2012).
lymph node metastasis (2 papers, 2014 to 2025). "Patients exhibiting high PSAT1 and SLC1A5 expression were more likely to develop lymph node metastasis, while high PHGDH, PSPH and SLC1A5 expression were associated with distant metastasis." (PMID 40660426, 2025).
nasopharyngeal carcinoma (2 papers, 2019 to 2022). A carcinoma arising from the nasopharyngeal epithelium. "In patients with nasopharyngeal carcinoma, the low expression of trans-splicing produced SEPT7P2-PSPH chimeric RNA induced the expression of downstream gene PSPH, promoting cell proliferation and metastasis/invasion, and transforming ability in vitro." (PMID 35627126, 2022).